CD274 (CD274 molecule)
Diseases named in the same sentence as CD274 in open-access papers (continued):
Sharing a sentence is not in itself a finding about the gene and the disease.
cancer (continued). "The upregulation of CD274 (PD-L1), FAM3C, and other T cell exhaustion markers in NRF2 activated LUAD cancer suggest that they could be the population who can benefit the most from anti-PD1 or anti-PD-L1 therapy." (PMID 38241355, 2024). "In cancer cells, lactylation of H3K18 can activate nuclear pore membrane protein 121 (POM121), which facilitates the nuclear translocation of MYC, its binding to the CD274 promoter, and the induction of PD-LI expression." (PMID 39516356, 2024). "Furthermore, we assessed the correlations between GBP4 and immune checkpoint genes, including TIGIT, CTLA4, CD274 and PDCD1, across cancers." (PMID 38347243, 2024). "For multiple immunosuppressive agents, KDR and CD274 showed the most significant negative correlation with METTL1 in almost all cancers." (PMID 39289775, 2024). "Furthermore, TOP1 was found to regulate several T cell regulatory genes including CD274 and CD276, which serve as markers of limiting T-cell effector response or anti-cancer immunity." (PMID 39156107, 2024). "Additionally, it was illustrated that ANKRD27 expression showed a positive correlation with the level of inhibitory immune checkpoints, such as CD274, PDCD1, CTLA4, and HAVCR2, across various types of cancer." (PMID 39834932, 2024). "Also, in most of the cancers, there was a significant correlation between UBE2C gene expression and CD96, CD274, CSF1R, KDR, and PDCD1LG2." (PMID 38577722, 2024). "In addition, we also itemized the correlations between TAGLN2 and the major immune checkpoints in pan-cancer, including LAG3, PDCD1, CTLA4, CD274, and TIGIT." (PMID 37476180, 2023). "The results demonstrated that SERPINE1 expression was positively correlated with the expression of most inhibitory immune checkpoints, including CD274 (PD-L1), PDCD1 (PD-1), CTLA4, and HAVCR2 (TIM-3) in most cancers, especially GBM-LGG, KIPAN, UVM, PAAD, and COAD-READ." (PMID 37680718, 2023). "PD-L1, also known as CD274 or B7H1, is highly expressed on the cell surface of antigen-presenting cells and cancer cells, whereas PD-1 (CD279) is expressed on the surface of immune cells such as T-cells, B-cells, natural killer (NK) cells, macrophages, monocytes, and dendritic cells." (PMID 37511619, 2023). "Studies have shown that antibodies against CD274, CTLA-4, and PDCD1 (immune checkpoint molecules) could promote antitumor T cell activity and improve clinical outcomes in various cancers." (PMID 37851374, 2023). "The positive correlation between MTHFR and CD274 in COAD, suggesting that COAD with higher expressed MTHFR may be a suitable candidate cancer type for PD-L1 therapy." (PMID 37354330, 2023). "Furthermore, positive correlations of PRC1 and some immune checkpoint genes (CD274, CTLA4, HAVCR2, LAG3, PDCD1, PDCD1LG2, TIGIT, and CD86) were observed in several cancers, especially BLCA, BRCA, KIRC, LUAD, LIHC, PRAD and THCA." (PMID 37563591, 2023). "Thus, six major ICs for cancer immunotherapy were analyzed in this work, namely CTLA4, PDCD1, CD274, ICOS, LAG3, and CD40." (PMID 37215135, 2023). "Furthermore, a notable heterogeneity was observed in the relationship between Eph receptors/EFN ligands and main checkpoints (CD274, PDCD1, CTLA4, and LAG3) in different types of cancer." (PMID 37637034, 2023). "CCNA2 was positively correlated with expressions of CD274, CTLA4, HAVCR2, LAG3, PDCD1, and TIGIT in most cancer types, which indicated the CCNA2 expression may act as a marker after immunotherapy." (PMID 35480884, 2022). "Notably, in GBM cancer cells, CD274 (PD-L1), PDCD1LG2 (PD-L2), LGALS9 (Galectin-9), and PVR (CD155) were correlated with m6A regulators." (PMID 35558067, 2022). "Besides, our research manifested the correlation of SLC7A11 with 8 IC genes, namely CD274 (also known as PD-L1), HAVCR2, LAG3, SIGLEC15, PDCD1LG2, CTLA4, PDCD1, and TIGIT in 33 cancer types." (PMID 36267158, 2022).
cancer (continued). "In the vast majority of 33 cancers, gene co-expression analysis showed that RIPK2 was positively correlated with the expression of immune checkpoint markers, such as PDCD1 (PD-1), CD274 (PD-L1), CTLA4 and TIGIT." (PMID 35508972, 2022). "Moreover, the link between CTLA4, PDCD1, CD86, CD274, and ISCA1 in various cancer types was measured." (PMID 36072584, 2022). "For diverse immune inhibitors, KDR and CD274 demonstrated the most significant negative relationship with METTL1 among nearly all cancers." (PMID 35432338, 2022). "Overall, these data indicated that CD274 and PDCD1LG2 could be established as biomarkers of therapeutic value in various cancers." (PMID 36276934, 2022). "Herein, we screened the co-expression level of CD274/PDCD1LG2 using TCGA and Genotype-Tissue Expression (GTEx) databases and found that these expression levels were related to treatment outcomes in patients with cancer." (PMID 36276934, 2022). "As for CD274, only SP140L correlated negatively in five cancer types." (PMID 36614001, 2022). "Interestingly, we observed that CD274 and PDCD1LG2 expression levels were correlated with contradictory prognoses in different cancers." (PMID 36276934, 2022). "In addition, the results uncovered that the expression of ADAM17 was positively correlated with an immunostimulator (IL6R) and immunoinhibitors (CD274, KDR, TGFBR1) in most cancer types." (PMID 35720350, 2022). "In addition, we studied the relationship between the expression of KCC2 (SLC12A5) and NKCC1 (SLC12A2) in pan-cancer and immune checkpoint genes, including SIGLEC15, IDO1, CD274, HAVCR2, PDCD1, CTLA4, LAG3, and PDCD1LG2." (PMID 35372048, 2022). "Prospective clinical trials such as the phase II trial studying the efficacy of Nivolumab and Ipilimumab in patients with rare cancers (NCT02834013) are currently enrolling patients with CD274 amplifications, defined as at least 6 copies of CD274 detected through CGP." (PMID 35598202, 2022). "The binding of CTLA-4 to another protein expressed on antigen-presenting cells (APCs), such as the B7 family (CD80, CD86, CD274, CD275, CD276, CD273, CD277), keeps the T cells in the inactive state, rendering them unable to kill other cells, including cancer cells." (PMID 36009853, 2022). "Interestingly, the expression levels of CD274 and PDCD1LG2 differed quite much among these cancer types, identified by TCGA databases." (PMID 36276934, 2022). "In addition, CD274 and PDCD1LG2 expression has been observed to be sex-dependent in HNSC and some other cancer types." (PMID 36276934, 2022). "Patient RNA-seq data from fifteen cancer types were accessed on cBioPortal to determine the role of PDCD1/CD274 in patient survival and to identify positively and negatively correlated genes, which were also assessed for clinical relevance." (PMID 34067485, 2021). "PD-L1 (CD274) is a cell surface molecule of the B7 family that may be expressed by immune cells and cancer epithelial cells to inhibit T cell proliferation and induce apoptosis upon binding to its ligand PD-135." (PMID 34732817, 2021). "In addition, LAG-3 co-expression with other immune checkpoint molecules such as CD274 and IDO1 in TILs serve as a prognostic biomarker for cancer prognosis." (PMID 34067904, 2021). "Discovery of the B7 family immune checkpoints such as CTLA-4 (CD152), PD-1 (CD279), as well as their ligands B7-1 (CD80), B7-2 (CD86), B7-H1 (PD-L1, CD274), and B7-DC (PD-L2, CD273), has opened new possibilities for cancer immunotherapy using monoclonal antibodies (mAb)." (PMID 33419027, 2021).
cancer (continued). "Many types of gastrointestinal cancer have shown promising outcomes after checkpoint blockade immunotherapy; however, it remains largely unclear about the expression profiles of programmed death 1 (PD-1) ligands (CD274 and PDCD1LG2) in the context of human pan-cancer." (PMID 33833994, 2021). "Furthermore, CSCs exert immunosuppressive functions including the expression of the immune checkpoints such as CD274 (best known as PD-L1) and CD80 (also known as B7.1) by preventing T cell activity and cancer dormancy." (PMID 34572009, 2021). "In some drug-resistant cancer cells, hyperactivated JNK/c-Jun signaling suppressed the histone deacetylase 3 (HADC3) expression, thereby elevating the histone H3 acetylation of the CD274 promoter." (PMID 33413496, 2021). "It binds to two ligands, PD-L1 (CD274) and PD-L2 (CD273), on cancer cells or immune infiltrates." (PMID 34885221, 2021). "By correlating drug sensitivity with the gene expression of cancer cell lines (n = 670), we identified Dasatinib, a potent Abl/Src inhibitor, with the efficacy negatively correlated with several immune biomarkers (CD274, CD47, PDCD1LG2), that are preferentially expressed by cancer cells." (PMID 32824422, 2020). "Therefore, we decided to study the relationship between CD274 (PD-L1) gene expression and the two major UPR pathways, IRE1α and PERK, across multiple human cancers." (PMID 32520957, 2020). "Due to recent advantages in cancer therapy, immune checkpoint inhibitors (ICIs) are new classes of drugs targeting programmed cell death protein 1 (PD-1) or its ligand programmed cell death protein 1-ligand 1 (PD-L1, synonym CD274, B7 homolog 1) and are used in many cancer therapies." (PMID 33552089, 2020). "One of the ways non-immune cells, including cancer cells, promote immune-suppression and induction of tolerance is by expressing PDL1 (also known as B7.H1 or CD274), a ligand for PD1 expressed by T cells." (PMID 31105556, 2019). "As a critical mediator that was overexpressed in various types of cancer, PD-L1 (programmed death-ligand 1, shown as CD274, also known as B7H1) was also observed to be up-regulated in OSCC cells by P. gingivalis infection, although the underlying mechanism was unclear." (PMID 30847302, 2019). "Among all the inhibitory immune mediators, the pathway consisting of the programmed cell death protein 1 (PD-1) and its ligands PD-L1 (B7-H1, CD274) and PD-L2 (B7-DC, CD273) has become a relevant tool for the great development that current cancer immunotherapy has achieved in recent years." (PMID 31075880, 2019). "Given the higher expression of PDCD1, CD274 and PDCD1LG2 in pre-RA and RA synovial biopsies, and the development of IA in cancer patients, we reasoned that PD-1 pathway may be down-modulated in RA patients." (PMID 29489833, 2018). "High-level and focal amplifications of CD274 have been described in a variety of human cancer entities, but so far not in CLL." (PMID 29463802, 2018). "PD-L1 (also called B7-H1 or CD274), which is expressed on many cancer and immune cells, plays an important part in blocking the ‘cancer immunity cycle’ by binding programmed death-1 (PD-1) and B7.1 (CD80), both of which are negative regulators of T-lymphocyte activation." (PMID 29163797, 2017). "Third, CD274 and PDCD1LG2 were deleted in some cases of TCGA NSCLC and CCLC cancer cell lines." (PMID 28977839, 2017). "Importantly, PD-L1 (CD274), an immune inhibitory receptor ligand whose inactivation using antibodies is being currently used for cancer treatment successfully, is underexpressed in c1." (PMID 28405244, 2017). "Moreover, we provide conclusive evidence that the immune modulator CD274 is another novel target of miR-93/106b, not only in BM (stromal) cells but also in M-MDSC and primary cancer cells." (PMID 28423491, 2017).
cancer (continued). "Emerging clinical data highlight the importance of one inhibitory ligand and receptor pair as an immune checkpoint: the programmed death-ligand 1 (PD-L1; B7-H1 and CD274) and programmed death receptor-1 (PD-1; CD279), in preventing the killing of cancer cells by cytotoxic T-lymphocytes." (PMID 27145284, 2016). "Considering the closest flanking genes of intergenic SNPs, the following are noteworthy and could contribute to the carcinogenic process, as has been reported for other cancer types: PRDM1, ATG5, MYC, EID, RLN1, CD274." (PMID 23626673, 2013). "While cancer cell-intrinsic CD28 facilitates immune escape by functioning as a non-classical RNA-binding protein to stabilize CD274 (PD-L1) mRNA, inhibiting this pathway in cancer cells without impairing essential T cell CD28 costimulation remains a major structural challenge." (PMID 42261788, 2026). "Moreover, the pan-cancer analysis did not reveal a significant correlation between CD274 and S100A1 mRNA expression in multiple types of solid tumors." (PMID 40090947, 2025). "Interestingly, multiple genes encoding cell surface immune checkpoint receptors and their ligands were transcriptionally regulated by IRF4, including PD-L1 (CD274), PD1 (CD279), CTLA4 (CD152), B7-2 (CD86), LAG3 (CD223), and PD-L2 (CD273), in these virus-infected cancer cells." (PMID 40733503, 2025). "Interestingly, canonical immune checkpoint molecules such as CD274 (PD-L1), which is known to be upregulated in various cancers to promote immune escape, was not upregulated in MYCN-A tumors." (PMID 39860532, 2025). "Besides, for K-M survival curves (OS), CD274 expression is correlated with survival in patients with ACC, SKCM, LGG and THYM cancers, which suggests that CD274 expression correlates with the prognosis of the four cancers." (PMID 38166842, 2024). "The negative correlation with CD274 (PD-L1), a key immune checkpoint molecule involved in cancer immune evasion, suggests that higher PIGF expression may be associated with lower PD-L1 levels in HNSCC, potentially reducing immune suppression." (PMID 39431157, 2024). "Furthermore, this system can be used to evaluate the sensitivity of cancers in individual patients to immunotherapies targeting cytotoxic CD8+ T cells, such as monoclonal antibodies against PD-1 (also known as PDCD1) and PD-L1 (or CD274)." (PMID 38258518, 2024). "In addition to the quantity of immune cells, the activity of immunoregulatory signalling pathways, such as the co-inhibitory pathway of programmed death ligand 1 (PD-L1, CD274) and its receptor programmed death 1 (PD-1, PDCD1), may affect cancer progression." (PMID 37002343, 2023). "Interestingly, ATXN3 appears to positively regulate PD-L1 expression at the transcriptional level, since real-time reverse transcription PCR analysis confirmed that Atxn3 targeting dramatically inhibited Cd274 mRNA expression in both LLC1 and B16 mouse cancer cells." (PMID 38038129, 2023). "In addition, DHX9 expression in most cancer types had an obvious positive correlation with several checkpoints, such as TGFBR1 (transforming growth factor-beta receptor 1), KDR (vascular endothelial growth factor receptor-2, VEGFR-2), and CD274 (PD-L1)." (PMID 37214432, 2023). "Additionally, In the cancer patients treated with anti-PDCD1 (Pembrolizumab), anti-CD274 (Atezolizumab), or anti-CTLA4 (Ipilimumab) of the K-M plotter database, elevated KLRB1 expression exhibited better OS and progression-free survival (PFS) after grouping with KLRB1 expression median value." (PMID 37988189, 2023). "Biomarkers such as PD-1 (programmed cell death 1 or PDCD1), PD-L1 (programmed cell death 1 ligand 1 or CD274 molecule), and CD8, in addition to microsatellite instability (MSI), have been recognized as valuable markers for indicating immunotherapy in other types of cancer." (PMID 37511658, 2023).
cancer (continued). "Many previous studies have reported the cancer‐promoting potential of USP22, including the induction of cell proliferation and DNA repair, activation of c‐Myc/NAMPT/SIRT1‐dependent FOXO1 and YAP signaling, and deubiquitination of CD274 to suppress anticancer immunity." (PMID 34743406, 2022). "Notably, SLC2A1 is remarkably positively correlated with CD274 (PD-L1) and CTLA4 in most cancers." (PMID 36358765, 2022). "We also analyzed the correlation between PD-L1 and PD-1 expression values and m6AScore, and the results showed that 23 out of 33 cancers had a significant correlation between m6AScore and CD274; 20 out of 33 cancers had a significant correlation between m6AScore and CD8A." (PMID 35265626, 2022). "However, some promising results have also been found in PD-L1 negative cancers, and, on the contrary, no results have been reported in high CD274 CRC." (PMID 36013315, 2022). "However, integrated studies considering CD274 and PDCD1LG2 across cancers remain limited." (PMID 36276934, 2022). "Anti-CD47 and anti-CD274 could blockade CD47 and CD274 expression on 4T1 cancer cells." (PMID 30872703, 2019). "Inhibition of the blocking responses to T cell activation using anti-PDCD1, anti-CTLA4, or anti-CD274 antibodies has proven clinically to result in improved responses for a subset of patients with metastatic melanoma, NSCLC, and potentially other forms of cancer." (PMID 28822103, 2018). "Programmed cell death ligand-1 (PD-L1), also known as B7-H1 and CD274, functions by interacting with its cognate receptor programmed cell death-1 (PD-1) to negatively regulate T cell functions, and therefore plays a pivotal role in the immune evasion of many cancer types." (PMID 30373602, 2018). "Current criteria for identifying cancer patients suitable for immunotherapy with immune checkpoint blockers (ICBs) are subjective and prone to misinterpretation, as they mainly rely on the visual assessment of CD274 (best known as PD-L1) expression levels by immunohistochemistry (IHC)." (PMID 27911273, 2017). "However, pan-cancer analysis of CD274 regulation in human pan-cancer has not yet been clarified." (PMID 38166842, 2024). "On the other hand, the overexpression of the CD274 gene encoding PD-L1 was found in deep transcriptome analysis, while the metabolism- and angiogenesis-related genes were upregulated in T15M samples compared to control T15 and T12 CD4+ cells, which were not exposed to cancer cells." (PMID 34439305, 2021). "The presence or absence of PD-L1 (or CD274) expression on tumors is known to be an important predictor of response to ICIs and is typically upregulated on T-cells in cancer in response to antigen presentation." (PMID 41008842, 2025). "Patients who did not respond to immunotherapy had cancer tissues with elevated BMP6 and FN1 expression, in contrast to those who responded, where CD274, HOXB5, and PPIL3 were more expressed." (PMID 40642086, 2025). "Similarly, vital immune checkpoint genes such as HAVR2, CD274, CTLA4, ITGB2, ICAM1, CCL5, CXCL10 all exhibited robust correlation with IFI30, and this immunotherapy might, in the future, establish a bond with IFI30, bringing new opportunities for cancer treatment." (PMID 39925804, 2025). "Its ligands PD-L1 (B7-H1, CD274) and PD-L2 (B7-DC, CD273) are expressed in a variety of cell types—leukocytes, nonhematopoietic cells, and cancer cells." (PMID 38646546, 2024). "Regarding gene expression, cancer immune evasion-related genes were found up-regulated in the negative BL samples, such as CD274 (alias PD-L1), IDO1, LAG-3, CTLA4, and CD80 and CD86 genes, required for the activation of the inhibitory activity of CTLA4." (PMID 34680332, 2021). "Wild-type ARID1A and ARID1B are located at the promoter of CD274 in OCCC cells (shown in the human OVCA429 and RMG1 cell lines, as well as mouse ovarian ID8-Defb29/Vegf cancer cells), although ARID1B was not able to influence the levels of CD274 in ARID1A knockout (KO) cells." (PMID 39272926, 2024).
cancer (continued). "The CAFDL signature was significantly positively associated with TGFB1, CD276, CD40, VEGFA, VEGFB, etc., but showed significantly negative correlation with immune checkpoints (such as CD274, PDCD1, CTLA4, TIGHT, and HAVCR2) and anti-cancer immune regulators (IFNG, IDO1, and GZMA)." (PMID 35967425, 2022). "Notably, transcripts for PD-1 (Pdcd1) were observed only in T cell clusters whereas PD-L1 (Cd274) transcripts were more abundant in neutrophils, DCs and macrophages and PD-L2 (Pdcd1lg2) in DCs and not in EGFR+ cancer cells." (PMID 35624211, 2022).